WNT5A (Wnt family member 5A)
Diseases named in the same sentence as WNT5A in open-access papers (continued):
Sharing a sentence is not in itself a finding about the gene and the disease.
breast carcinoma (continued). "Furthermore, even in the presence of lactate, breast cancer cells expressing WNT5A showed a statistically significant reduced level of MCT1 as compared to lactate treated MDA-MB-468-EV cells (p = 0.006)." (PMID 29069720, 2017). "Although rWNT5A clearly triggers WNT5A signaling in breast cancer cells, the stability of rWNT5A in cell culture conditions remains unknown." (PMID 29069720, 2017). "Our finding that WNT5A signaling inhibits the expression of the key lactate importer, MCT1, suggests a mechanism whereby WNT5A counteracts the effect of extracellular lactate in breast cancer cells and thereby their ability to migrate and disseminate to form metastatic lesions." (PMID 29069720, 2017). "To investigate activation and outcome of the Ror2-dependent non-canonical Wnt signaling pathway, we overexpressed the Ror2 receptor in MCF-7 and MDA-MB231 breast cancer cells, stimulated the cells with its ligand Wnt5a, and we knocked-down Ror1 in MDA-MB231 cells." (PMID 28695110, 2017). "In the present study, we demonstrated that increased migration induced by extracellular lactate was impaired in WNT5A-transfected breast cancer cells, thereby suggesting that WNT5A might inhibit lactate uptake in breast cancer cells." (PMID 29069720, 2017). "Interestingly enough, the drug-candidate Foxy5 (WNT5A-mimic hexapeptide) also inhibited breast cancer cell migration in the presence of exogenous lactate, suggesting a therapeutic potential for Foxy5 in managing breast tumors with high glycolytic activity." (PMID 29069720, 2017). "Thus, we conclude that WNT5A signaling impairs prostate and breast cancer metastases differently and in each case via several parallel mechanisms." (PMID 28886116, 2017). "Similar to breast cancer, Wnt5a effect on ovarian cancer is also controversial." (PMID 28491097, 2017). "Conversely, Borcherding and colleagues found that Wnt5a could inhibit the expansion of tumor-initiating cells in breast cancer." (PMID 26942462, 2016). "WNT-5A activates CDC42 in various cell types including breast cancer cells." (PMID 26514730, 2016). "Microglia induced breast cancer MCF-7 cell invasion in the brain in a Wnt5a-dependent manner, suggesting a mechanism whereby microglia may potentiate brain metastasis." (PMID 27571105, 2016). "Furthermore, we present evidence that a three-gene set—WNT5A, CNGA2 and IGSF9B—was associated with shorter survival in breast cancer patients." (PMID 28097125, 2016). "In order to test this hypothesis, we set out to examine whether exogenous Wnt5a could impact tumor proliferation in breast cancer cells through the regulation of rDNA transcription." (PMID 27500936, 2016). "The low abundance of WNT-5A in breast cancer cells could be attributed to epigenetic silencing of the WNT-5A promoter." (PMID 26514730, 2016). "However, the ability of WNT5A to inhibit breast cancer cell migration and invasion is an EMT-independent mechanism that, at least in part, can be explained by decreased CD44 expression." (PMID 27623766, 2016). "Moreover in breast cancer, where Wnt5a is known to act as a tumor suppressor through inhibition of canonical Wnt signaling, a new perspective on the role of Wnt5a in inhibiting mammary carcinoma initiation was revealed." (PMID 27571105, 2016). "Wnt5a expression was observed in TAMs in human breast cancers and colon cancers." (PMID 27608847, 2016). "Furthermore, expression of WNT pathway genes correlated with estrogen receptor (ER) expression, especially WNT5a and WNT5b, with approximately 50% of breast cancer tissues overexpressing these genes." (PMID 27487128, 2016). "WNT5A-treated breast cancer cells did not exhibit changes EMT markers, which led us to hypothesize that WNT5A suppresses the migration and invasion of breast cancer cells via an EMT-independent mechanism(s)." (PMID 27623766, 2016). "Therefore, we next analyzed the expression of CD44 protein in breast cancer cells stably expressing WNT5A protein." (PMID 27623766, 2016).
breast carcinoma (continued). "Thus, WNT5A inhibits the migration and invasion of breast cancer cells via an EMT-independent mechanism." (PMID 27623766, 2016). "Moreover, we present evidence that a three-gene set—WNT5A, CNGA2, and IGSF9B—can be used as a signature associated with shorter survival in breast cancer patients." (PMID 28097125, 2016). "We previously demonstrated that WNT5A inhibits ERK1/2 signaling in breast cancer cells." (PMID 27623766, 2016). "Notably, we have previously demonstrated that breast cancer cells transfected with the WNT5A plasmid exhibit low migration and invasion compared to control MDA-MB-468-EV cells." (PMID 27623766, 2016). "In this study we investigated whether the secreted protein Wnt5a, an antagonist of mammary tumor growth, regulates rRNA synthesis in breast cancer cells." (PMID 27500936, 2016). "In the context of human breast cancer, both epidemiological and functional data have implicated Wnt5a as a tumor suppressor and our data indicating that Wnt5a signals through DVL1 to inhibit rRNA synthesis provide a novel mechanism underlying that role." (PMID 27500936, 2016). "Because the WNT5A-mediated inhibition of breast cancer cell migration and invasion was independent of EMT reversal, we explored the involvement of alternative pathways that might be triggered by WNT5A to curb the spread of breast cancer cells." (PMID 27623766, 2016). "Our results demonstrate that WNT5A signaling affects the expression of the transmembrane glycoprotein CD44, and WNT5A is known to alter the splicing of CD44 and its variant isoforms in breast cancer." (PMID 27623766, 2016). "However, there are also reports that Wnt5a functions as a tumor suppressor in breast cancer, thyroid cancer, and colon cancer." (PMID 25779663, 2015). "There is increasing evidence that Wnt5a is a tumor suppressor in breast cancer." (PMID 24944588, 2014). "PIAS1 acts by delineating histone modifications and DNA methylation to silence the expression of a subset of clinically relevant genes, including breast cancer DNA methylation signature genes such as cyclin D2 and estrogen receptor, and breast tumor suppressor WNT5A." (PMID 24586797, 2014). "Contradictory effects of Wnt5a have been demonstrated in breast cancer." (PMID 24944588, 2014). "It is possible that these contradictory results could be due to different properties of the cell lines investigated and that this might reflect different functional properties of Wnt-5a in the different subgroups of breast cancer." (PMID 23990917, 2013). "However, in vitro experiments on human breast cancer cells have reported contradictory results, indicating both a tumor suppressive and promoting functions of Wnt-5a." (PMID 23990917, 2013). "Finally, to show that the WNT‐5A‐induced inhibition of MDA‐MB468 breast cancer cell migration is dependent on reduced MMP9 activity, we studied MDA‐MB468‐5A cell migration in the absence and presence of active human recombinant MMP9." (PMID 23727359, 2013). "Indeed, Wnt5a acts as a stimulator of metastasis in gastric cancer cells, but as a suppressor in breast cancer cells." (PMID 24156409, 2013). "Low expression of WNT5A is correlated with poor prognosis in breast cancer patients." (PMID 23484019, 2013). "However in a breast cancer context the effects of prolonged WNT‐5A exposure on cell migration would be more relevant for how WNT‐5A affects breast cancer metastasis." (PMID 23727359, 2013). "The purpose of the present study was to evaluate whether Wnt5a expression has a unique prognostic value in premenopausal breast cancer patients that could explain the contradictory in vitro findings of the effect of Wnt5a on breast cancer cells." (PMID 23990917, 2013). "Recently these findings have been confirmed and in addition it was shown that when 4T1 breast cancer cells were transfected to express Wnt-5a their injection into the tail vein of Balb/c mice resulted in significantly less lung metastases as compared to control cells." (PMID 23990917, 2013).
breast carcinoma (continued). "In experimental studies, we found that reconstitution of Wnt-5a signaling decreased the migratory capacity and invasiveness of cultured breast cancer cells and that administration of a Wnt-5a-mimicking peptide significantly reduced breast cancer metastases in a mouse model." (PMID 23990917, 2013). "Therefore, an in-depth understanding of the mechanism of WNT5A action in breast cancer progression and metastasis is required." (PMID 23484019, 2013). "Based on the present results we deemed it necessary to assess whether Wnt-5a affects breast cancer cell invasion differently in ER-positive compared to ER-negative breast cancer cells." (PMID 23990917, 2013). "Consequently, we highlighted Cdc42 as a downstream mediator of non‐canonical WNT‐5A signaling in breast cancer cells and suggest an essential role of Cdc42 activation in reducing breast cancer cell migration and invasion." (PMID 23727359, 2013). "Finally, we and others have shown that WNT5A expression is down-regulated in human breast carcinomas and plays a tumor suppressor role by inhibiting proliferation and/or metastasis." (PMID 24260410, 2013). "In contrast to the hypothesis that Wnt5a functions as a tumor suppressor, Wnt5a secreted by macrophages is proved to be essential for macrophage-induced invasiveness of breast cancer cells." (PMID 22655072, 2012). "Constitutively active ΔDAD-Daam1 induced RhoA activation, the formation of stress fibers, and migration of MCF-7 cells, indicating that Daam1 may be specifically required for the activation of Dvl2 after Wnt5a treatment in breast cancer cells." (PMID 22655072, 2012). "We also used siRNA to knock down Dvl2 expression in breast cancer cells and checked whether Wnt5a-induced cell migration could be inhibited." (PMID 22655072, 2012). "One gene which could be targeted in this antagonistic pathway is Wnt-5a, which has been shown to act as a suppressor of tumor metastasis in breast cancers." (PMID 22363760, 2012). "Since rWnt5a decreased the invasion of 22Rv1 and DU145 cells, invasion assay was also performed in these cell lines using Foxy5 which is a hexapeptide derived from the amino acid sequence of Wnt5a protein and previously shown to inhibit motility of breast cancer cells like rWnt5a." (PMID 22039506, 2011). "We can speculate in cells with mutated CK1ε that Wnt5a will predominantly signal via the Rac-1/JNK and NFAT pathways, thus promoting breast cancer cell invasion and tumor aggressivity." (PMID 20507565, 2010). "Here we test the hypothesis that TGF-β and Wnt5a can antagonise Wnt/β-catenin signalling and redirect mammary tumour phenotype." (PMID 19344510, 2009). "Similarly, another study showed that TAMs in breast cancer biopsies express WNT5A." (PMID 36982422, 2023). "miR-665 targets TRIM8 to regulate the Wnt5a/β-Catenin and Caspase-3 signaling pathways in lung squamous carcinoma to promote cell proliferation and inhibit apoptosis; miR-665 is associated with poor prognosis and promotes metastasis by targeting NR4A3 in breast cancer." (PMID 38097567, 2023). "For example, higher VD levels were associated with lower methylation of Wnt Family Member 5A (WNT5A) and dickkopf 1 (DKK1) genes in colorectal cancer patients and higher methylation of Retinoid X Receptor Alpha (RXRA) and NAD Synthetase 1 (NADSYN1) genes in breast cancer patients." (PMID 36430854, 2022). "Therefore, the early termination of adjuvant drug therapy for breast cancer may lead to a high recurrence rate of Wnt5a-positive breast cancer." (PMID 34047951, 2021). "However, treatment of serum-starved breast-cancer PDX cells with exogenous Wnt5a could enhance the level of phosphorylated cortactin within 5 min." (PMID 31667337, 2019).
breast carcinoma (continued). "Nonetheless, we found that cirmtuzumab could inhibit the capacity of Wnt5a to induce tyrosine phosphorylation of cortactin in serum-starved ROR1+breast-cancer PDX, even at Wnt5a concentrations of 100 ng/ml, indicating that the Wnt5a-induced phosphorylation of cortactin was dependent on ROR1." (PMID 31667337, 2019). "We therefore screened for a WNT5A-mimicking peptide and finally, after screening several peptide sequences, we identified a formylated six amino acid peptide named Foxy5 that was found to mimic the signaling and functional effects of rWNT5A on breast cancer cells." (PMID 30171384, 2018). "Furthermore, it has been suggested that microglia may be one of the signaling entities for breast cancer cell metastases in the brain, since the microglia of organotypic brain cultures produce high levels of Wnt5a, promoting the growth of breast cancer." (PMID 30123112, 2018). "Interestingly, in a recent study from our lab, WNT5A and its mimic Foxy5 has been shown to reduce breast cancer cell migration even in the presence of high lactate levels, suggesting its therapeutic potential in managing highly glycolytic breast tumors as well." (PMID 30171384, 2018). "Therefore, it was of interest to find a molecule mimicking the tumor suppressor effects of WNT5A on breast cancer cells that could also be used in vivo." (PMID 30171384, 2018). "In breast cancer, WNT5A-S mRNA expression was elevated, while WNT5A-L mRNA was decreased, thereby suggesting that if these different mRNA isoforms are translated to different WNT5A isoforms that they might have distinct biochemical functions." (PMID 30171384, 2018). "However, breast cancer is a heterogeneous disease that may lead to mixed responses to WNT5A signaling in different breast cancer studies." (PMID 30171384, 2018). "However, to our best knowledge, expression of MUC5AC has so far neither been linked to invasive breast cancer nor been reported as a potential target of Wnt5a signaling." (PMID 28695110, 2017). "Based on the findings that WNT5A can reduce β-catenin activity in colon cancer cells and that β-catenin signaling induces aerobic glycolysis in breast cancer cells, we explored the possibility that WNT5A impairs aerobic glycolysis in breast cancer cells via impaired β-catenin signaling." (PMID 29069720, 2017). "Moreover, this study aimed to determine whether inhibition of such a mechanism could explain our previous observation that WNT5A can suppress the invasion of breast cancer cells." (PMID 27623766, 2016). "Therefore, we hypothesized that reduced levels of CD44 are responsible for the WNT5A-mediated reduction in the migration and invasion of breast cancer cells." (PMID 27623766, 2016). "Therefore, we next investigated whether the WNT5A-mediated reduction in CD44 decreased PI3K/AKT signaling in breast cancer cells." (PMID 27623766, 2016). "Additionally, the low WNT-5A expression could also be due to posttranslational suppression of WNT-5A mRNA in breast cancer cells by HuR proteins." (PMID 26514730, 2016). "However, we also examined whether WNT5A inhibits breast cancer cell migration/invasion via a reversal of EMT in breast cancer cells." (PMID 27623766, 2016). "Consequently, we hypothesized that long-term exposure to WNT5A is required to induce EMT reversal in breast cancer cells." (PMID 27623766, 2016). "However, neither the rWNT5A treatment of nor stably transfecting the WNT5A protein into breast cancer cells produced any changes in EMT markers, although WNT5A signaling still inhibited the migration and invasion of both breast cancer cell lines under similar conditions." (PMID 27623766, 2016). "Thus, Wnt5a is essential for macrophage-induced invasiveness in breast cancer." (PMID 24944588, 2014).
breast carcinoma (continued). "Given the heterogeneity of breast cancer, the present identification of Wnt5a as a potential prognostic biomarker and an indicator of novel future therapies that might aid in further improving the survival of pre menopausal patients with ER+ breast cancers." (PMID 23990917, 2013). "Thus, the role of Wnt5a in premenopausal breast cancer has until now been unclear." (PMID 23990917, 2013). "The increased tumor cell invasiveness, independent of cell proliferation, caused by loss of Wnt-5a might in such tumors promote breast cancer cell dissemination and the formation of micro-metastases." (PMID 23990917, 2013). "Our present results show that Wnt5a expression is a marker of favourable outcome also in premenopausal breast cancer patients and that it is a particularly valuable prognostic marker and thus a possible therapeutic target in pre-menopausal breast cancer patients with ER+ tumors." (PMID 23990917, 2013). "However, Wnt5a signaling in breast cancer progression remains poorly defined." (PMID 22655072, 2012). "With exception of VANGL2, up-regulation of the genes involved in Wnt signaling pathway, namely WNT5A, MSX2, TCF7L2 and TNFRSF11B, was confirmed in the validation set, further emphasizing the important role of the Wnt signaling pathway in PIK3CA-mutated breast cancer." (PMID 21209903, 2010). "Expression of WNT5aL and WNT5aS induced invasiveness of the luminal A breast cancer cell line MCF7, similar to the treatment with recombinant WNT5a." (PMID 40165582, 2025). "In breast cancer, FOSL2-expressing CAFs mediate VEGF-independent angiogenesis through the transcriptional activation of WNT5A, revealing novel anti-angiogenic therapeutic strategies targeting the tumor stroma." (PMID 41430036, 2025). "In breast cancer, estrogen induces FOSL2/Wnt5a expression via cAMP/PKA signaling, in turn, the secreted Wnt5a regulates FZD5/NK-kB/ERK signaling in vascular endothelial cells to promote tumor angiogenesis." (PMID 38233872, 2024). "In contrast, the HS578T-Hyg breast cancer cells are in a M state due to the expression of “classical” M markers, such as CDH2, VIM, ZEB1 and WNT5A." (PMID 38139138, 2023). "Expression of WNT5A/B and β-catenin were correlated with markers of the cancer stem cell (CSC) phenotype, and AHR-antagonist treatment of MDA-MB-231 or SUM149 breast cancer cells resulted in significantly lower levels of WNT5A RNA." (PMID 36077068, 2022). "WNT5A and its signaling pathway are novel mechanisms by which ATBF1 contributes to breast cancer tumorigenesis." (PMID 36476423, 2022). "The interaction of Twist and BRD4 at the enhancer and promoter of WNT5A promote the expression of WNT5A, which leads to the activation of WNT signal pathway to accelerate EMT and tumorsphere formation in basal-like breast cancer cells." (PMID 35216622, 2022). "In this context, Foxy-5 was able to impair the motility of breast cancer cell lines with low levels of endogenous WNT-5A and to reduce the early metastatic spread of WNT-5A-low prostate cancer cells in an orthotopic mouse model." (PMID 34771683, 2021). "Our study showed that in vitro Rlip deficiency inhibits EGF endocytosis and downstream signaling from WNT5A to ERK and PIK3CA, which are key proteins involved in the oncogenesis and natural history of breast cancer." (PMID 32498332, 2020). "While WNT5A protein expression was found to be low in 75% of TNBC tumors, medium to high expression was detected in 75% of ER+ breast cancer samples." (PMID 32083079, 2020). "Wnt5a and Wnt5b have been proven as regulators of EMT in breast cancer, and we also corroborated this conclusion." (PMID 31462314, 2019). "b mRNA expression of WNT3A, WNT3, WNT5A, WNT5B, and WNT11 in five different breast cancer subtypes based on bc-GenExMiner v4.1 according to the Sørlie’s subtypes (****p < 0.0001; Red star: the former > the latter; Green Star: the former < the latter)." (PMID 31462314, 2019).